CRP (C-reactive protein)
Diseases named in the same sentence as CRP in open-access papers (continued):
Sharing a sentence is not in itself a finding about the gene and the disease.
myocarditis (continued). "The finding that a significantly higher percentage of patients with ASS with myocarditis, compared with those without myocarditis, had fever and increased CRP levels at ASS clinical onset suggests that an inflammatory phenotype does exist and that myocarditis is one of the primary clinical features." (PMID 37796832, 2024). "Usually, laboratory tests including inflammatory markers C-reactive protein (CRP), erythrocyte sedimentation rate (ESR), and procalcitonin are elevated in keeping with ongoing inflammation; however, normal values do not exclude myocarditis." (PMID 35903566, 2022).
Cirrhosis (140 papers, 2013 to 2026). A chronic disorder of the liver in which liver tissue becomes scarred and is partially replaced by regenerative nodules and fibrotic tissue resulting in loss of liver function. "First, the role of CRP-mediated inflammatory pathways in the association of myopia with liver fibrosis and cirrhosis requires mechanistic validation using in vitro and in vivo models." (PMID 40869686, 2025). "Patients with cirrhosis have high systemic inflammation (TNFα, CRP, and IL-6) that is associated with poor outcomes." (PMID 39733165, 2024). "Cirrhosis is associated with SI, as evidenced by increased white blood cell count, neutrophils, activated circulating monocytes, plasma CRP, pro-inflammatory cytokines, macrophage activation markers, and systemic oxidative stress." (PMID 39337069, 2024). "An increase in IL-6 and TNF-α levels in patients with cirrhosis is involved in CRP production, suggesting that changes in CRP are linked to changes in these inflammatory cytokines." (PMID 36983211, 2023). "There are reports in which increased CRP levels have been indicated to be associated with increased mortality in patients with cirrhosis." (PMID 37834802, 2023). "The presence of multiple oral diseases was associated with higher CRP, indicating a degree of systemic inflammation activation beyond that associated with cirrhosis itself." (PMID 33553670, 2021). "In conclusion, the patients had a high prevalence of various oral diseases, which was associated with the higher presence of cirrhosis complication status and higher CRP and nutritional risk score." (PMID 33553670, 2021). "This cohort study showed that cirrhosis patients had highly prevalent multiple oral diseases, which were associated with increases in cirrhosis complications, CRP, and nutritional risk score." (PMID 33553670, 2021). "Of note, previous studies identified some noninvasive models associated with mortality in patients with cirrhosis, including albumin-bilirubin score and C-reactive protein to albumin ratio." (PMID 34055994, 2021). "Strong inflammatory conditions displayed by high levels of C-reactive protein (CRP) or soluble CD163 (sCD163) are associated with an unfavorable prognosis in patients with cirrhosis." (PMID 26121590, 2015). "However, conventional biomarkers such as procalcitonin (PCT) and C-reactive protein (CRP) have limited diagnostic accuracy for detecting infections in patients with cirrhosis." (PMID 41354872, 2025). "In patients with compensated cirrhosis, elevated CRP ≥ 5 mg/L was strongly linked to a significant reduction in M-HDL (p = 0.038), S-HDL (p < 0.001), and XS-HDL (p = 0.013) subclass concentrations, while L-HDL (p = 0.052) concentrations showed only a non-significant trend." (PMID 40563298, 2025). "However, in another study of mixed‐etiology decompensated cirrhosis, while CRP was reported to be significantly linked with infection, only the neutrophil‐to‐lymphocyte ratio predicted survival in patients hospitalized for cirrhotic decompensation." (PMID 38961593, 2024). "The CRP level was found to be the best diagnostic marker for infection in patients with cirrhosis." (PMID 37761321, 2023). "Furthermore, ALD patients had high CRP levels at baseline, thus highlighting this high-risk population among patients with cirrhosis." (PMID 37616205, 2023). "Additionally, chronically increased CRP is associated with disease severity in a number of comorbidities, such as cardiovascular disease or cirrhosis." (PMID 32423000, 2020). "Thus, it appears that CRP is relatively less diagnostic value of infection in patients with advanced cirrhosis." (PMID 30097024, 2018). "In addition, CRP level was reported associated with a lower response rate to antibiotics, a higher mortality rate in cirrhosis patients with SBP." (PMID 26498833, 2015).
Cirrhosis (continued). "Our data therefore supports the use of IL-6, along with leukocyte count, CRP, bilirubin, and serum creatinine, as potential biomarkers to monitor disease progression and the inflammatory burden associated with EF DNA positivity in patients with decompensated cirrhosis and ACLF." (PMID 41189884, 2025). "Indeed, serum levels of the pro-inflammatory cytokine interleukin-6 (IL-6), tumor necrosis factor-α (TNF-α), C-reactive protein, and lipopolysaccharide are elevated in patients with cirrhosis in parallel with the severity of disease, and are associated with poor outcomes." (PMID 35545763, 2022). "Albumin and CRP are serological inflammation-based markers and involved in the progression of cirrhosis." (PMID 41149065, 2025). "In conclusion, high myopia is independently associated with an increased risk of liver fibrosis and cirrhosis in individuals with elevated AST (≥40 U/L), with a small portion of this association being mediated by CRP." (PMID 40869686, 2025). "We examined the association between inflammation (C-reactive protein levels) and HDL subclass distribution in cirrhosis." (PMID 40563298, 2025). "CRP was significantly affected by cirrhosis (p = 0.007) and the bacterial growth*cirrhosis interaction (p = 0.014)." (PMID 41007066, 2025). "According to Grønkjaer, patients with cirrhosis and AP had more cirrhosis-related issues and lower albumin levels and higher CRP." (PMID 40308406, 2025). "Although C-reactive protein is higher at the beginning of cirrhosis due to systemic inflammation, as the condition progresses, the liver's synthetic ability wanes, and the level of CRP lowers even when infection is noted." (PMID 41555935, 2025). "As such, inflammatory markers such as serum CRP and procalcitonin have been proposed to aid in the diagnosis of cirrhosis." (PMID 39961976, 2025). "INR, bilirubin, creatinine, and CRP levels increased significantly from compensated cirrhosis to ACLF (p < 0.05), whereas hemoglobin and albumin levels decreased significantly with advancing severity (both p<0.001)." (PMID 41200179, 2025). "Systemic inflammatory response plays a crucial role in the progression of cirrhosis, and CRP is a surrogate marker for systemic inflammatory response." (PMID 41149065, 2025). "We built repeated measures ANOVA models to evaluate changes in WBC, PCT, and CRP in relation to bacterial growth and cirrhosis." (PMID 41007066, 2025). "Age, sex, BMI, serum TC, FBG, ALT, Hs-CRP, triglycerides (TG), serum total bilirubin (Tbil), hepatitis B surface antigen positive (HBSAg(+)), cirrhosis, smoking, drinking, exercise, fatty liver, and education degree." (PMID 41199849, 2025). "Specifically, the AUC values of hs-CRP in predicting significant fibrosis, advanced fibrosis, and cirrhosis in patients with MASLD were all approximately 0.6." (PMID 39995674, 2025). "The modest mediation effect of CRP suggests that systemic inflammation has a limited but discernible effect on the relationship between myopia and liver fibrosis and cirrhosis." (PMID 40869686, 2025). "GlycA levels were lower, while hs-CRP levels were higher in patients with cirrhosis compared to PREVEND participants (p < 0.001)." (PMID 39859175, 2025). "SB reduced the serum TNF-α and IL-6 levels in experimental carbon tetrachloride-induced cirrhosis in rats and also reduced the level of CRP in one RCT with decompensated cirrhosis patients." (PMID 39203520, 2024). "Among compensated versus decompensated cirrhosis, the average decompensated sweat biomarker values measured during the study period were slightly higher in both CRP and IL6." (PMID 39733165, 2024). "In a previous study, a low LCR, or in other words, a high CRP-to-lymphocyte ratio, was an effective prognostic marker in patients with cirrhosis." (PMID 39685802, 2024).
Cirrhosis (continued). "For instance, the role of CRP (as an acute phase protein) in acute inflammatory response is destabilized in cirrhosis with a relatively higher basal CRP level resulting in attenuated response during infection." (PMID 38961593, 2024). "In obese patients, it is not only CRP secretion, but also dietary factors such as the consumption of high calorie foods which contributes to non-alcoholic fatty liver with inflammation, cirrhosis, and ultimately hepatocellular carcinoma." (PMID 38742193, 2024). "MPV, NLR, and serum CRP levels are the three indicators that can be used to diagnose SBP in cirrhosis and ascites." (PMID 37559036, 2023). "CRP levels are higher in patients with cirrhosis than in healthy subjects and are involved in decompensation and mortality." (PMID 36983211, 2023). "Again, there exist an old case report on false-positive CRP test results in a case with hepatic cirrhosis, as revealed by a latex agglutination method [1160]." (PMID 37873776, 2023). "CRP is synthesized in the liver hence, in situations such as liver failure, hypoproteinemia or cirrhosis, CRP levels are lower." (PMID 36671362, 2023). "Markers representing the severity of inflammation (CRP) and cirrhosis (total bilirubin and Child–Pugh score) were also important for AKI and HRS–AKI and combined in the prediction models." (PMID 37567912, 2023). "Sex (p = 0.001), cirrhosis (p < 0.001), and CRP (p = 0.016) were the significant predictors of plasma adiponectin levels." (PMID 38137508, 2023). "Various studies have suggested that the cut-off CRP level for the diagnosis of infection in patients with cirrhosis is between 20 and 80 mg/L." (PMID 37559036, 2023). "Another study of patients with cirrhosis revealed serum IL-6 and CRP levels as independent predictors of mortality and liver transplantation." (PMID 37799767, 2023). "Previous studies have identified several common blood indices related to the SBP in cirrhosis, including CRP and NLR." (PMID 37951894, 2023). "Despite the widespread use of Child-Pugh and MELD scores as predictive models of cirrhosis progression, several investigators advocate the use of alternative laboratory indices, including CRP levels." (PMID 35308545, 2022). "We also found by univariate analysis a significant positive association between CRP (β = 0.256, p = 0.029), AST (β = 0.310, p = 0.008), triglycerides (β = 0.268, p = 0.022), and advanced liver fibrosis and cirrhosis in the lean group." (PMID 35453849, 2022). "In the setting of advanced cirrhosis, the diagnositic performance of C-reactive protein (CRP) for endotoxemia is poor than that of procalcitonin." (PMID 35721053, 2022). "The CRP values exceeded the threshold of 5 mg/dL in all patients with cirrhosis and in only one of the controls." (PMID 34884173, 2021). "In line with previous findings, markers of inflammation (CRP, leukocytes and IL-6) were significantly elevated in patients presenting with decompensated cirrhosis in this cohort." (PMID 34654829, 2021). "This patient had advanced cirrhosis with a preoperative albumin level of 2.8 g/dL, a preoperative CRP value of 29.7 mg/L, and a FAR of 0.124 g/L, indicating end-stage disease with a low hepatic synthetic capacity." (PMID 33592030, 2021). "The risk of PLC also increased with the increase of hs-CRP when participants were stratified by sex, HBV infection, and cirrhosis." (PMID 33256656, 2020). "A similar correlation between systemic ZO-1 levels and an inflammatory marker (C-reactive protein; CRP) was observed in patients with cirrhosis." (PMID 32120994, 2020). "A large study in a total of 368 patients with cirrhosis revealed significantly higher CRP and PCT levels in the case of clinically overt infections." (PMID 32899730, 2020).
Cirrhosis (continued). "Culture-positive organisms per se do not seem to trigger systemic inflammation assessed by two representative cytokines in patients with cirrhosis as demonstrated by the blood and ascites culture results in the two sub cohorts stratified by their CRP profile." (PMID 30800122, 2019). "In patients with cirrhosis serum bilirubin, C-reactive protein level and INR were higher than in controls (3.07 vs. 0.96 mg/dL; 36.9 vs. 5 mg/L; 1.53 vs. 0.95; p < 0.001, respectively)." (PMID 31781297, 2019). "Several studies have shown the reliability of PCT and CRP for the diagnosis of infection during cirrhosis with important AUC." (PMID 31582968, 2018). "We evaluated the effectiveness of WBC, PCT, and CRP measurements in predicting infection in decompensated cirrhosis using the assessment of ROC curves." (PMID 31582968, 2018). "Our results showed that PCT and CRP serum levels were significantly higher in the BI group, and thus, these markers were useful in the diagnosis of BI in decompensated cirrhosis." (PMID 31582968, 2018). "Our cirrhosis cohort had increased CRP, to a large extent attributable to cirrhosis as a chronic inflammatory condition." (PMID 29439734, 2018). "Regarding BI in patients with decompensated cirrhosis, CRP maintains efficiency slightly higher than that of the PCT without being discriminative." (PMID 31582968, 2018). "Considering the inflammatory process, the result show persistently elevated CRP levels in patients with cirrhosis." (PMID 29658815, 2018). "Although having been considered a more sensitive indicator of renal function in cirrhosis, CysC is influenced by factors independent of GFR which are frequently present in patients with cirrhosis such as elevated CRP or low serum albumin levels." (PMID 26627205, 2015). "The present study revealed that CRP and NLR are useful diagnostic markers for infection compared to the SIRS in hospitalized cirrhosis patients." (PMID 26498833, 2015). "First, elevated serum CRP levels can be affected by coexistent cirrhosis, which is common in patients with chronic HBV infection." (PMID 25602444, 2015). "The aim of our study was to assess a possible association between plasma inflammatory biomarkers (CRP, IL-6, soluble CD14) and the extent of fibrosis or cirrhosis using a FibroScan® in HIV/HCV co-infected patients." (PMID 23527135, 2013). "Inflammatory markers, including white blood cell count (p = 0.007) and C-reactive protein (p < 0.001), were markedly elevated in the decompensated cirrhosis group, while lipid parameters, specifically total cholesterol and HDL cholesterol, were significantly lower (p < 0.001)." (PMID 40563298, 2025). "CRP has been shown to have questionable value in patients with cirrhosis." (PMID 39961976, 2025). "The partially mediated effect of CRP suggests that systemic inflammation may be involved in the co-morbid mechanism of high myopia and liver fibrosis and cirrhosis." (PMID 40869686, 2025). "Notably, in patients with decompensated cirrhosis, CRP has been shown to outperform procalcitonin and leukocyte count for detecting bacterial infection." (PMID 40993724, 2025). "Our study provides intriguing evidence that continuous noninvasive monitoring of inflammatory biomarkers may predict outcomes – as patients with cirrhosis had higher evening and nocturnal levels of sweat CRP and IL6 when compared with healthy controls." (PMID 39733165, 2024). "Sweat monitoring nocturnal CRP/IL6 elevations in cirrhosis versus controls." (PMID 39733165, 2024). "Multivariate logistic regression analysis identified the following six factors as risk factors for 30-day mortality: performance status (PS) ≥ 2, albumin level < 3.0 g/dL, blood urea nitrogen (BUN) ≥ 25 mg/dL, C-reactive protein (CRP) ≥ 1.0 mg/dL, comorbid metastatic cancer, and cirrhosis." (PMID 38438534, 2024).
Cirrhosis (continued). "SB reduced the serum concentrations of TNF-α, IL-1β, IL-6, and IL-4 in animals with metabolic dysfunction-associated steatotic liver disease (MASLD); lowered the serum TNF-α and IL-6 levels in experimental cirrhosis in rats; and reduced the CRP levels in decompensated cirrhosis." (PMID 39203520, 2024). "In particular, patients with liver cancer or cirrhosis with high CRP levels show poor prognoses." (PMID 36899958, 2023). "Therefore, CAR, a combined marker of CRP and albumin, is suggested to be a crucial indicator in patients with cirrhosis." (PMID 36983211, 2023). "CRP and albumin are closely related in patients with cirrhosis." (PMID 36983211, 2023). "However, because CRP is produced by the hepatocytes in response to inflammation, the use of the serum CRP level as a biomarker of inflammation or infection in cirrhosis has been contested." (PMID 37019645, 2023). "At the same time, inflammatory markers (i.e., CRP and IL-6), along with RAS components, were elevated with more severe ACLD, indicating a state of coagulation/fibrinolysis activation linked to RAS activity—that reportedly is upregulated in cirrhosis." (PMID 34945736, 2021). "Having one and up to four oral diseases compared with no oral disease was associated with the presence of more cirrhosis complications (46.7 vs 20.5%), higher CRP (28.5 vs 10.4 mg/L), and nutritional risk score (4 vs 3)." (PMID 33553670, 2021). "Recently, some data suggested that CRP may be one of the prognostic factors for cirrhosis and cancer." (PMID 35223421, 2021). "In this study, we aimed to learn whether PCT and CRP would be helpful as early markers of BI in patients with cirrhosis and to evaluate their prognostic value in terms of mortality." (PMID 31582968, 2018). "Thus, CRP appears to reflect the inflammatory cascade probably induced or contributed to by bacterial translocation resulting in decreased SVR in cirrhosis." (PMID 28146577, 2017). "In the 102 patients with ascites caused by cirrhosis, lactoferrin levels in the ascitic fluid were significantly correlated with ascitic WBC count, ascitic PMN count, serum PMN count, serum platelet level, serum CRP, serum PT-INR, and the Child-Pugh score." (PMID 27733127, 2016). "Prevalence of hepatic CD68+AXL+ cells significantly decreased with cirrhosis progression: (healthy, 90.2%; Child-Pugh A, 76.1%; Child-Pugh B, 64.5%; and Child-Pugh C, 18.7%; all P < .05) and negatively correlated with Model for End-Stage Liver Disease and C-reactive protein (all P < .05)." (PMID 37004869, 2023). "Therefore, CRP and related inflammatory cytokines may be key targets for improving liver functional reserve in patients with cirrhosis." (PMID 36983211, 2023). "However, care must be taken when interpreting the CRP results in patients with cirrhosis." (PMID 37559036, 2023). "Finally, it seems that CRP may allow for the prediction of early mortality in cirrhosis patients following esophageal variceal bleeding." (PMID 37873776, 2023). "Additionally, the metabolism of omega-6 polyunsaturated fatty acid produces pro-inflammatory products including lipid mediators and indirectly C-reactive protein; which have been implicated in causing fibrosis in MAFLD, subsequently cirrhosis and ultimately HCC." (PMID 33430001, 2021). "The experimental and control groups were comparable in terms of age, sex, HBV status, cirrhosis history, alanine aminotransferase, AFP positivity, and SAA/CRP levels." (PMID 40660552, 2025). "The features that were retained included age, AFP, HVB, liver failure type, cirrhosis, DBIL, TBIL, CRP, retinol, pre-albumin, platelets, PT, cholinesterase, TT, and monocytes." (PMID 41220690, 2025). "A persistently elevated level of CRP, a biomarker of inflammation, is shown to be better than SIRS in predicting short-term mortality in cirrhosis." (PMID 40114845, 2025). "A meta-analysis showed that both CRP and PCT had satisfactory accuracy in the diagnosis of bacterial infection in patients with cirrhosis." (PMID 38769522, 2024).